FAAH (fatty acid amide hydrolase)
Diseases named in the same sentence as FAAH in open-access papers (continued):
Sharing a sentence is not in itself a finding about the gene and the disease.
depression (61 papers, 2012 to 2026). "Altered activity of fatty acid amide hydrolase (FAAH), an enzyme of the endocannabinoid system, has been implicated in several neuropsychiatric disorders, including major depressive disorder (MDD)." (PMID 33494322, 2021). "Moreover, the CAF PF group displayed a significant increase in FAAH in mPFC, which was previously associated with decreased expression of miRNAs coupled with depression." (PMID 39582223, 2025). "However, in individuals with mild/severe depressive symptoms, the concentrations of all three NAEs are highly associated, suggesting either that FAAH becomes a more active enzyme or that NAAA a less important regulator of PEA concentrations in depression." (PMID 38273283, 2024). "Moreover, it was suggested that the polymorphism in the FAAH gene was associated with bipolar disorder and major depression which is in line with the importance of FAAH activity in depression and suicidal behavior." (PMID 36831868, 2023). "FAAH gene functional polymorphisms, particularly rs324420 SNP, whichleads to reduced FAAH activity, have also attracted attention to evaluating their role in depression." (PMID 35563156, 2022). "First, variants of the FAAH gene may be related with susceptibility to mood disorders such as major depression." (PMID 32395111, 2020). "Furthermore, polymorphism in FAAH gene is shown to be associated with bipolar disorder and major depression." (PMID 22606285, 2012). "Thus, we evaluated whether the response to exposure therapy was greater for subjects with the FAAH C385A polymorphism, across both treatments and by comorbid depression." (PMID 35896533, 2022). "In response to stressors, such as in the chronic unpredictable stress or the chronic mild stress models of depression, FAAH can initiate the degradation of AEA, thus reducing AEA-CB1 signaling." (PMID 40550956, 2025). "This convergence has prompted the development of dual FAAH/TRPV1 inhibitors which have shown dose-dependent antidepressant-like effects in rodent models of depression, underscoring the therapeutic relevance of this pathway." (PMID 40806746, 2025). "One of the earliest studies to investigate the interaction between probiotics and FAAH modulation demonstrated that inhibiting FAAH can alleviate depression-like symptoms in stressed rats." (PMID 38891799, 2024). "For example, it was shown relatively early that knocking out the CB1 receptor results in depression-like behavior, while inhibition of the FAAH enzyme reduces depression." (PMID 38931356, 2024). "As such, it seems unlikely that there will be a therapeutic role for FAAH inhibitors in the treatment of depression." (PMID 37671673, 2023). "Although FAAH is known to be involved in depression mechanisms in animal studies (the most recent examples), much more investigation is needed to ensure the same mechanisms are relevant to humans." (PMID 36835237, 2023). "A recent study analyzed the plasma concentrations of 2-AG and AEA and the CNR1, FAAH, and MGLL polymorphisms as predictors of depression severity six months after suffering a traumatic injury." (PMID 35563156, 2022). "The aim of this scoping review was to establish the role of FAAH expression in animal models of depression to determine the translational potential of targeting FAAH in clinical studies." (PMID 33494322, 2021). "In summary, there is a large consensus across studies that inhibition of FAAH, using a range of inhibitors, is effective for producing antidepressant-like effects and restoring a normal phenotype on various behavioral tests of depression." (PMID 33494322, 2021). "The maternal deprivation model of depression has also been used to assess FAAH gene expression in male and female rats." (PMID 33494322, 2021). "For example, we would expect that primarily internalizing disorders, including major depressive disorder or posttraumatic stress disorder, would display higher brain FAAH density." (PMID 33462180, 2021).
depression (continued). "A literature search employing multiple databases was performed; all original articles that assessed FAAH expression in animal models of depression were considered." (PMID 33494322, 2021). "Nevertheless, the effects of the inhibition of FAAH need to be further analyzed in other models that mimic the features of depression like the chronic unpredictable stress model (CUS) to understand their role in neurogenesis and behavior." (PMID 33833828, 2021). "This review aimed to establish the role of FAAH in animal models of depression to determine the therapeutic value of targeting FAAH in clinical studies." (PMID 33494322, 2021). "Β- caryophyllene and dibutyl phthalate could directly act on CHRM1, FAAH, CNR2, SLC6A2, and SLC6A3, which were associated with anesthesia, attention deficit hyperactivity disorder, and major depressive disorder." (PMID 40729010, 2025). "On the contrary, the four other gene variants analyzed (CYP3A4 rs2242480, CYP3A4 rs35599367, CNR17B rs1049353, and FAAH rs2295632) as other variables (other drugs and painkillers taken, depression, and anxiety conditions) remained very far from being significant." (PMID 37509416, 2023). "However, only a few clinical trials performed till now support the assumption that FAAH plays an important role in depression mechanisms." (PMID 36835237, 2023). "Finally, in Wistar Kyoto (WKY) rats, another genetic animal model of depression, increased FAAH and CB1r binding levels while lower levels of AEA were found in the PFC and HIPP." (PMID 35563156, 2022). "Levels of the endocannabinoid anandamide (AEA) seem to affect these depression-by-stress-related features and could be modulated by fatty acid amide hydrolase (FAAH)." (PMID 33833828, 2021). "Furthermore, there have only been two studies of an animal model of depression where a FAAH inhibitor is administered concomitantly with an antidepressant: one being a TCA (e.g., imipramine) and the other being an SSRI (e.g., fluoxetine)." (PMID 33494322, 2021). "In conclusion, the current animal models of depression show that FAAH gene expression and protein levels are dysregulated in the brain; specifically, there is increased FAAH gene expression and protein activity in the PFC, hippocampus and striatum, which correlates with the depressive phenotype." (PMID 33494322, 2021). "This study was aimed at evaluating if the effects of chronic inhibition of FAAH could be capable of restoring neurogenesis and behavioral impairment in mice subjected to a depression model by CUS." (PMID 33833828, 2021). "The aim of this scoping review was to evaluate the role of brain FAAH in depression in animal models and behavioral tests of depression, such as the chronic mild stress and forced swim test paradigms, to determine the therapeutic value of targeting FAAH in clinical trials." (PMID 33494322, 2021). "Furthermore, associations have been found between gene polymorphisms in CNR1, CNR2 (genes coding for CB1R and CB2R, respectively) and FAAH genes and behaviours characteristic of depression." (PMID 26483037, 2016). "Therefore, it is possible that the doses used in this study were not sufficient to inhibit FAAH activity and that a more widespread inhibition of FAAH activity in other brain regions in the neural circuitry of depression, such as the PFC, is required to rescue depressive phenotypes." (PMID 33494322, 2021). "Additionally, the majority of studies on FAAH in animal models of depression used male mice and rats; this is the case in most animal studies largely due to the assumption that female estrous cycles may confound the effects of experimental manipulations." (PMID 33494322, 2021). "The discrepant finding could also be due to differences in the animal model and species strain used across studies; this study used Flinders Sensitive Line rats, a genetic model of depression, whereas another study assessing FAAH protein levels used Sprague–Dawley rats and a CMS model." (PMID 33494322, 2021).
depression (continued). "While there is some optimism for a potential role for FAAH inhibition in the treatment of PTSD and anxiety disorders, the same cannot be said for depression, another stress-related psychiatric disorder." (PMID 37671673, 2023). "Less common FAAH inhibitors, such as JZL195, PF3845 and SSR411298, have also been used in animal models of depression." (PMID 33494322, 2021). "Pioneering work in this field, conducted by the Piomelli group, includes the potent antidepressant-like effects elicited by a FAAH inhibitor, seemingly due to elevated levels of AEA, in the mouse models of depression, tail suspension and forced swim tests." (PMID 26483037, 2016). "Indeed, preclinical studies using inhibitors of hydrolysing enzymes such as FAAH and MGL have shown that ECs have beneficial effects on CNP and depression." (PMID 39545479, 2025). "Future studies could explore the potential of simultaneous inhibition of FAAH and MAGL to enhance endocannabinoid signaling for treating depression-like behaviors." (PMID 40787242, 2025). "The role of the endocannabinoid system (ECS) in major depressive disorder (MDD) is under-investigated despite reports of increased activity and/or concentration of fatty acid amide hydrolase (FAAH), a key ECS enzyme, in fronto-limbic brain regions in some animal models of depressive behavior." (PMID 40550956, 2025). "In a study on major depressive disorder, it was verified that circSTAG1 can bind to the demethylase ALKBH5 in the mouse hippocampus, decreasing ALKBH5 levels to alter the m6A level of FAAH mRNA and limit FAAH expression." (PMID 36212687, 2022). "There are other classes of antidepressants, besides TCAs, which have not been investigated with respect to FAAH gene expression or protein activity in animal models of depression." (PMID 33494322, 2021). "Hence, inhibition of FAAH and MAGL that indirectly increases the excitability of the endocannabinoid system by reducing the hydrolysis of endocannabinoids could be a more promising therapeutic approach against depressive disorders." (PMID 33833828, 2021).
Obesity (56 papers, 2010 to 2026). Accumulation of substantial excess body fat. "A polymorphism in FAAH (FAAH C385A) reduces FAAH expression, increases anandamide levels, and increases the risk of obesity." (PMID 37039453, 2023). "Other animal and human works have described increased eCBs concentrations linked to a reduced central and peripheral expression of FAAH in obesity, being this enzyme even proposed as a potential biomarker of BE." (PMID 37254556, 2023). "For example, fatty acid amide hydrolase (FAAH) gene polymorphisms have been described in obesity, an enzyme aimed at eCBs degradation, specially AEA." (PMID 37254556, 2023). "The genetic variation in FAAH expression is associated with the hypophagic effects of leptin and obesity." (PMID 35565526, 2022). "To date, previous reviews have highlighted the genetic association between variation in the FAAH gene and obesity-related outcomes in humans." (PMID 34959715, 2021). "A cross-sectional study of 667 subjects identified racial differences in CNR1 and FAAH polymorphisms associated with obesity." (PMID 34220722, 2021). "Plasma endocannabinoids correlate positively with markers of obesity and metabolic disorders, and alterations to the genes encoding CB1, CB2, and FAAH have been associated, respectively, with metabolic syndrome and overweight and obesity." (PMID 34681224, 2021). "Study showed previously that excessive endocannabinoids concentrations in obesity are associated with decreased fatty acid amide hydrolase (FAAH) gene expression in adipose tissue." (PMID 26904688, 2016). "FAAH gene encodes fatty acid amide hydrolase and plays an important role in the development of obesity." (PMID 24621099, 2014). "Studies have shown that a missense polymorphism in the FAAH gene is associated with severe obesity (BMI≥40), along with increased plasma levels of anandamide (AEA), and related N-acylethanolamines." (PMID 22442717, 2012). "Functional in-vitro studies further revealed that the 129Thr variant decreased the expression and activity of FAAH in humans, thus seemingly corroborating the implication of the A-allele at rs324420 in human obesity." (PMID 20044928, 2010). "The only coding variant commonly found in the subjects in this obesity study was the FAAH 385 C→A (P129T) as previously reported." (PMID 20098695, 2010). "We initially assessed association of five single nucleotide polymorphisms (SNPs) in FAAH with early onset extreme obesity in up to 521 German obese children and both parents." (PMID 20044928, 2010). "The FAAH SNP rs324420 A-allele has recently been reported to be associated with drug and alcohol abuse and obesity." (PMID 20044928, 2010). "The genetic association of FAAH with obesity is interesting because many previous studies with common variants have failed in identifying significant associations." (PMID 20976246, 2010). "At the present time, there are four human clinical studies investigating the association of the functional FAAH P129T mutation with obesity." (PMID 20098695, 2010). "The aim of this study was therefore to test for association of selected gene variants in FAAH with obesity." (PMID 20044928, 2010). "The set of rare variants in the FAAH promoter associated with BMI is also associated with increased level of FAAH substrate anandamide, further implicating a functional role in obesity." (PMID 21118518, 2010). "Other research teams reported that a single-nucleotide polymorphism in FAAH (rs324420) was associated with increased obesity and may contribute to altered leptin sensitivity in humans, though there are discrepancies between the outcomes of different studies." (PMID 41096816, 2025). "In our results, the FAAH rs324420 SNP was positively associated with TNFα levels (p = 0.039), in line with other studies where this SNP has been associated with increased BMI and obesity, as well as markers of systemic inflammation, such as TNFα levels." (PMID 40431452, 2025).
Obesity (continued). "In this regard, gene × environment interactions could govern whether the FAAH C385A genotype affects obesity susceptibility under particular environmental contexts." (PMID 37039453, 2023). "FAAH encodes one of the best-characterized enzymes involved in the hydrolysis of bioactive lipids and serves as a potential therapeutic target for the treatment of obesity." (PMID 35565526, 2022). "The A-allele results in lower FAAH expression and has been associated with heightened obesity risk." (PMID 34959715, 2021). "In addition to examining associations between the FAAH C385A variant and obesity-related outcomes, four studies examined associations with other FAAH SNPs." (PMID 34959715, 2021). "Studies in rodent models showed that reduction in FAAH activity leads to increased body weight and metabolic function, and while the human genetic association studies found consistent evidence of association between FAAH variants and obesity, the direction of effect was inconsistent." (PMID 34959715, 2021). "Interestingly, a positive correlation to the BMI and body fat was found for the circulating levels of endocannabinoids, whereas obesity was linked to a reduced adipose expression of Cnr1 and FAAH." (PMID 31910153, 2020). "Our findings on the overexpression of key metabolic enzymes might also be useful for clinical research, as FAAH polymorphisms are associated with increased obesity in human subjects." (PMID 30108271, 2018). "Notably, a missense polymorphism in the FAAH gene is associated with obesity in humans and FAAH deficient mice have increased AEA levels in, e.g., the liver and show increased fat mass and body weight." (PMID 30687125, 2018). "Our findings suggest that plasma levels of AEA in combination with genotyping of the FAAH 385 variant and hsCRP may identify an endocannabinoid-related obesity phenotype in a population with complex interethnic admixture." (PMID 26561012, 2015). "In light of this background, the primary aim of the current study was to investigate if obesity co-morbidities and metabolic risk factors, including hyperinsulinaemia, hyperglycaemia and dyslipidaemia, influence FAAH and MGL enzyme activities in adipose tissue." (PMID 24593280, 2014). "Human FAAH gene mutations are associated with increased body weight and obesity." (PMID 22442717, 2012). "A further connection between FAAH and obesity has been identified via a missense mutation in the FAAH gene, which occurs in 3.6-10.8% of the population (depending on ethnicity) and is associated with obesity." (PMID 21813022, 2011). "Thus, more clinical studies with comparable subject cohorts are needed to evaluate the significance of the association of the FAAH 385 A mutant alleles with overweight and obesity." (PMID 20098695, 2010). "Since the relatively common FAAH P129T mutation has been associated with obesity in some studies, it is possible that other rare FAAH variants or MGLL variants may also contribute to ECS tonic activation in severely obese individuals." (PMID 20098695, 2010). "As our data were not corrected for multiple testing, we thus conclude that the FAAH variants analysed here may play a major role in the genetic etiology of obesity within our samples." (PMID 20044928, 2010). "As FAAH counteracts the orexigenic effects of endocannabinoids through their rapid degradation, genetic variation in FAAH that leads to decreased enzyme activity and thus increased levels of endocannabinoids might be implicated in the etiology of obesity." (PMID 20044928, 2010). "Furthermore, association with obesity had recently been reported for the A/A genotype of the FAAH SNP rs324420." (PMID 20044928, 2010). "The aim of this study was to analyse whether FAAH alleles are associated with early and late onset obesity." (PMID 20044928, 2010).